NGF (nerve growth factor)
Diseases named in the same sentence as NGF in open-access papers (continued):
Sharing a sentence is not in itself a finding about the gene and the disease.
tumor (continued). "Tumor tissue and immune cell derived endogenous substances such as nerve growth factor have the potential to cause sprouting of primary sensory nerve fibers with the net effect being bone pain." (PMID 29867498, 2018). "the NGF treatment can trigger the development of a more differentiated cell phenotype and as result cause the reduction or complete cessation of tumor growth and more interesting (ii)." (PMID 27439311, 2016). "Mounting evidence suggests that NGF not only affects tumor-associated cells but also dictates cancer cell behaviors." (PMID 25840418, 2015). "After metastasized into bone, cancer cells, as well as tumor associated immune cells, osteoblasts, osteoclasts secrete factors like nerve growth factor (NGF), prostaglandin E2 (PGE2) and endothelin." (PMID 23516587, 2013). "Currently, exosomes have been explored as drug delivery carriers, and NGF may be an adjunct to targeted therapy if it specifically binds to tumour-associated nerves or blood vessels." (PMID 40860871, 2025). "Dense axonal ingrowth driven by tumour-derived NGF has been associated with increased PD-1 expression on local T lymphocytes and a rise in M2-polarised macrophages, illustrating how neuronal inputs synchronise with immune checkpoints to maintain an immunosuppressive milieu." (PMID 41142827, 2025). "Moreover, NGF TrkA receptors and nerve fibres were particularly abundant in the walls of tumor-associated arteries, indicating a possible role for the NGF in angiogenesis." (PMID 40806192, 2025). "NGF can influence the polarization of tumor-associated macrophages (TAMs) within the TME." (PMID 38392180, 2024). "Furthermore, higher levels of NGF and TrkA have often been associated with tumor perineural invasion (PNI)." (PMID 38392180, 2024). "This novel molecular mechanism underlying the NGF‐NGFR communication in T‐cell proliferation could provide fresh insights for anti‐tumor immunotherapy." (PMID 38204220, 2024). "Elevated levels of NGF precursors are strongly associated with neurogenesis in prostate cancer, where tumors can reprogram recruited nerves to develop into an adrenergic infiltrating phenotype that supports tumor growth and invasion." (PMID 39492832, 2024). "Cetuximab resistance can also be mediated by the activation of the Akt signalling pathway in an alternative way, such as the overexpression of other growth factors (TGFβ, VEGF, and NGF) and their associated receptors by the tumour cells and/or the tumour microenvironment." (PMID 38002001, 2023). "Although NGF is associated with tumorigenesis, with advancements in delivery technology, precise drug delivery can also make NGF a potential drug for the treatment of neurological diseases in tumor patients." (PMID 38049878, 2023). "Notably, SBP-deficient PDAC cells have an inherent program to promote tumor innervation via increased secretion of the nerve growth factor (NGF)." (PMID 36139512, 2022). "NGF can also be secreted by tumor-associated immune cells and fibroblasts." (PMID 33392191, 2020). "The model was run under EGF and NGF stimulation conditions in the ALK1174L mutated tumor." (PMID 31480495, 2019). "Nonetheless, it is not clear whether and through which mechanisms neurotrophins, and especially NGF, may eventually be implicated in the modulation and refinement of tumor editing/escape." (PMID 31812953, 2019). "the effects of NGF can be persistent, all together supporting the hypothesis that NGF can reverse transformed properties of susceptible tumor cell progression." (PMID 27439311, 2016). "TrkA shows to mainly mediate the trophic effects of NGF, and the overexpression, rearrangement or mutation of the TrkA gene can result in constitutive activation of the receptor, which increased the tumorigenicity and tumor progression." (PMID 27835587, 2016). "Meanwhile, NGF may affect tumour invasion by regulating the activity of tumour-associated nerves." (PMID 40860871, 2025).
tumor (continued). "Additionally, experiments in mice show that NGF antibody treatment reduces bone damage caused by tumors, delays fracture time, and prolongs the use of tumor-carrying limbs, although the underlying mechanisms of these effects are unknown." (PMID 37007073, 2023). "Rather than simply causing the sprouting of existent nerves around the tumour, these mediators may also cause nerves to grow into the tumour, moving up NGF and VEGF gradients as well becoming hyperactive as demonstrated here through enhancement of sensory neuronal TRPV1 activity." (PMID 29100335, 2017). "In the tumor microenvironment, NGF-producing mast cells accumulate and activate ILC2s to induce regulatory T cells (Tregs), ultimately fostering tumor growth." (PMID 41723132, 2026). "Mechanistically, tumor cells secrete neurotrophic factors such as nerve growth factor, brain-derived neurotrophic factor, and glial cell-derived neurotrophic factor and release axon-guidance molecules such as ephrin B1 to promote axonogenesis." (PMID 41601691, 2026). "Elevated NGF levels significantly suppress the cytotoxicity of NK cells, thereby facilitating immune escape and supporting tumor growth." (PMID 41583906, 2026). "NGF can bind to its receptor tropomyosin receptor kinase A (TrkA), inducing directional invasion of tumor cells toward nerves." (PMID 41556039, 2026). "Stomach adenocarcinoma tissues exhibit significantly elevated sympathetic nerve density, driven by tumor cell‐derived NGF." (PMID 41556039, 2026). "They observed that PDAC cells upregulate NGF expression to promote tumor innervation in Ser/Gly deprivation." (PMID 41556039, 2026). "In the osteogenic bone niche, tumour-conditioned macrophages and osteoclast precursors can synthesise NGF, which in turn enhances ICAM-1-mediated monocyte adhesion and supports further macrophage infiltration." (PMID 41142827, 2025). "In OS, where endothelial activation and vascular patterning influence leukocyte entry and spatial organization, NGF-driven angiogenic signaling provides a credible mechanism for lymphocyte exclusion and myeloid-biased trafficking at tumor–bone interfaces." (PMID 41567220, 2025). "From a therapeutic perspective, targeting key molecular drivers of spontaneous neurogenesis—including NGF, GDNF, VEGF, and the TGF-β/Smad3 pathway underlying MNT—represents a promising approach to mitigating the adverse effects of tumor innervation." (PMID 41009819, 2025). "This sustained and specific fluorescence signal underscores the NGF probe's potential for tumor diagnosis." (PMID 40048021, 2025). "NGF is a neurotrophic factor secreted by neurons, tumor cells, and stromal components, playing a critical role in promoting tumor innervation and progression." (PMID 41009819, 2025). "In contrast, minimal fluorescence was detected in NRP1- and GLUT1-negative NCI-H1299 cells, underscoring NGF's selective targeting of NRP1-positive tumor cells." (PMID 40048021, 2025). "NGF’s excellent performance makes it a promising fluorescent molecular probe for tumor imaging and intraoperative navigation." (PMID 40048021, 2025). "The analysis revealed that cytokines, including IFN-γ, IL-1ra, IL-8, M-CSF, MCP-1, MIP-1α, and SCGF-β, were associated with tumor height, while β-NGF, GRO-α, IL-5, IL-9, MIP-1β, TNF-β, and VEGF were linked to tumor diameter." (PMID 41048959, 2025). "In exogenous serine-dependent PDAC, serine deprivation induced the expression of NGF to promote innervation and the release of serine by neurons to rescue tumor growth." (PMID 40243726, 2025). "Nevertheless, NGF can induce the reinnervation of perivascular nerves in prostate tumors in mice, leading to the suppression of tumor growth, possibly through the regulation of vascular tone and blood flow to the tumor." (PMID 40243726, 2025). "By blocking NGF-TrkA interactions, these therapies can reduce nerve infiltration into tumors and slow tumor growth." (PMID 41009819, 2025).
tumor (continued). "This phenomenon emerges intrinsically within the TME, driven by tumor-derived neurotrophic factors such as NGF, GDNF, and vascular endothelial growth factor (VEGF), which stimulate axonal sprouting and nerve fiber formation directly within tumors." (PMID 41009819, 2025). "Adrenergic nerves are known to positively regulate cancer cell proliferation through the activation of β-adrenergic receptors, which also mediate nerve growth factor (NGF) production and secretion, thereby promoting tumor innervation." (PMID 40243726, 2025). "This is consistent with our previous study indicating that NGF derived from tumor microenvironment is an important mediator of CRC metastasis." (PMID 39643827, 2025). "Cancer cell-derived NGF induces SC autophagy, which promotes a nerve repair-like response, thereby enhancing autophagic activity in tumor cells." (PMID 40861469, 2025). "Similar IL-1β and TNF-α inputs have been reported to modulate NGF and BDNF levels in bone-associated tumours, suggesting a broader principle whereby inflammatory mediators act as upstream rheostats of neurotrophic output." (PMID 41142827, 2025). "Collectively, our results showed that ZNF662 functioned as a tumor suppressor in TNBC through suppressing NGF signaling axis." (PMID 40612670, 2025). "At the same time, oral administration of larotrectinib, a TrkA inhibitor, significantly antagonized NGF-promoted M2 macrophage expression and tumor progression." (PMID 41301953, 2025). "Axons not only promote tumour proliferation but are also closely related to tumour‐derived nerve growth factor (NGF)." (PMID 40579785, 2025). "NGF is highly expressed in the tumor microenvironment and facilitates cancer progression by promoting the growth of sensory and sympathetic nerves." (PMID 39860039, 2025). "Flow cytometry and fluorescence imaging experiments confirmed that NGF effectively targets tumor cells expressing high levels of NRP1 and GLUT1, aligning with their respective expression profiles." (PMID 40048021, 2025). "The first prerequisite for clinical progress is molecular stratification that distinguishes tumours driven by ligand-dependent NGF-TrkA, BDNF-TrkB or GDNF–RET loops from those harbouring activating rearrangements or kinase-domain point mutations." (PMID 41142827, 2025). "NGF enhances the perineural invasion (PNI) capability of tumour cells by promoting the expression of exosomal miRNA‐21‐5p secreted by PC cells." (PMID 40579785, 2025). "Beta‐blockers, such as propranolol, bupranolol and metoprolol, have been investigated for their ability to reduce NGF expression, nerve density, and tumor progression in PDAC models." (PMID 40981722, 2025). "The nerve growth factor (NGF) and its receptor, tropomyosin receptor kinase A (TrkA), play critical roles in tumor progression, including angiogenesis, metastasis, and cancer-induced bone pain." (PMID 39860039, 2025). "Tumours recruit nerves and stimulate nerve outgrowth (tumour axonogenesis) via the secretion of axon guidance molecules, such as neurotrophins (e.g. nerve growth factor, NGF; brain-derived neurotrophic factor, BDNF) and exosomes." (PMID 41029717, 2025). "Tumors and tumor cell lines derived from these mice produce nerve growth factors (NGFs), and Tax trans-activates the NGF promoter through a Tax-responsive element exhibiting a 92% homology to the 21 bp repeats of the HTLV-1 LTR." (PMID 41153438, 2025). "The NGF is reported to be elevated in tumor cells of HCC, while both types of its receptors (TrkA and p75NTR) are present in Kupffer cells, endothelial cells and hepatic stellate cells, only in the liver cancer tissue." (PMID 40806192, 2025). "There findings underscore NGF’s potential in developing fluorescent probes for intraoperative tumor navigation." (PMID 40048021, 2025).
tumor (continued). "Mechanistic studies implicate neurotrophin and axon−guidance signaling (e.g., GDNF–RET, NGF–TrkA) and Schwann−cell reprogramming as drivers of neural tracking and extracellular−matrix remodeling at the nerve–tumor interface." (PMID 41445745, 2025). "Larotrectinib effectively inhibits NGF-induced tumor angiogenesis, showcasing its potential as a tumor-targeted therapeutic agent." (PMID 39860039, 2025). "Although NGF-differentiated PC12 neuron-like cells exhibit lower CD24 than tumor cells and reduced sensitivity to Cys-hMnO2@GOx@EM-CD24, neuro-safety still requires further validation, particularly in primary sympathetic neuron models and in juvenile mice." (PMID 41281650, 2025). "Growth factors such as EGF, vascular endothelial growth factor (VEGF), IGF-1, and nerve growth factor (NGF) secreted by tumor cells as well as stromal cells promote OSCC development and progression via activation of the PI3K/AKT signaling network." (PMID 40746882, 2025). "NE also upregulates NGF, particularly in pancreatic ductal adenocarcinoma, leading to enhanced neurite outgrowth and tumor innervation independently of β-adrenergic signaling." (PMID 41009819, 2025). "Although TRKA is considered a factor contributing to tumour regression, NGF can both protect NB cells from doxorubicin or enhance its action." (PMID 41511287, 2025). "Tumor innervation can be induced by cancer cells through the secretion of neurotrophins such as nerve growth factor (NGF), brain-derived neurotrophic factor (BDNF) and glial cell-derived neurotrophic factor (GDNF), amongst others." (PMID 40075699, 2025). "The exact molecular mechanism of the PNI of NGF- and TrkA-negative tumours is worthy of further study." (PMID 40783715, 2025). "In cancerous lesions, certain types of tumour cells secrete NGF, which leads to sensory and sympathetic nerve pathological sprouting and the formation of a neuroma-like structure." (PMID 40783715, 2025). "Conversely, as the tumor progresses, SCs secrete several pain-related molecules, such as the NGF, that promote the activation of primary sensory neurons, thus increasing nociceptive activity." (PMID 40806192, 2025). "In response, the decreased mTE of UC[C/U] Ser codons can allow the selective translation of UC[C/U]-poor genes, such as nerve growth factor, into the tumor." (PMID 41237252, 2025). "After serine deprivation, PDAC cells release more NGF, enhancing the movement of axons toward the tumor." (PMID 40427098, 2025). "The absence or presence of NGF in tumour microenvironment (TME) results in spontaneous regression or differentiation of NB cells, respectively." (PMID 41511287, 2025). "In the extracellular matrix (ECM) of ICCs, NGF expression is upregulated, which activates TrkA receptors on tumor cells through a paracrine mechanism, thereby promoting PNI." (PMID 40421086, 2025). "A similar phenomenon can also be observed in PDAC, and upregulated NGF rescues tumour cells from programmed death." (PMID 40783715, 2025). "These cells promote tumor proliferation and local nerve growth by releasing ACh and upregulating NGF, creating a self‐perpetuating cycle." (PMID 39492832, 2024). "In the present study, NGF/NGFR was correlated positively with PD‐1/PDL‐1 expression in both tumor tissue and healthy tissue, and the NGF‐NGFR communication inefficiency was demonstrated to suppress the proliferation of T cells." (PMID 38204220, 2024). "By understanding the downstream effectors and cross-talk with other signaling cascades, we can gain deeper insights into the regulation of tumor cell proliferation and survival by NGF." (PMID 38392180, 2024). "Decreased levels of CD3+ cells and CD8+ cells and increased tumor growth were observed in the IgG mAb‐exposed and NGF‐sh‐Lv/NGF‐sh‐rAd‐injected mice." (PMID 38204220, 2024). "Overall, the activation of NGF signaling pathways in cancer cells can contribute to aggressive tumor growth, metastasis, and therapy resistance." (PMID 38392180, 2024).
tumor (continued). "In this context, the present study revealed that NGF+ tumor cells, NGF− tumor cells, NGFR+ T cells, and NGFR− T cells appeared simultaneously in HCC patients." (PMID 38204220, 2024). "Tumor target drug gastrin-releasing peptide receptor (GRPR) antagonist RC-3095 reduces the secretion of NGF in COAD cells, suggesting that the reduction of neurotrophin secretion is a potential mechanism for the anti-proliferation effect of GRPR antagonists." (PMID 38694509, 2024). "Originally identified for its pivotal role in neuronal development and function, NGF has emerged as a critical player in the growth and survival of various tumor types." (PMID 38392180, 2024). "In PDAC, a tumor microenvironment with elevated glucose levels can promote the overexpression of NGF and its receptor, thereby synergistically promoting the occurrence of NI." (PMID 39766161, 2024). "Studies have confirmed that the secretion of NGF by tumors induces nerve regeneration, while promoting tumor cell survival, cell motility, and invasion." (PMID 38816365, 2024). "Beyond inhibiting tumor axonogenesis, anti‐NGF antibodies also offer the benefit of alleviating cancer‐related pain, demonstrating their dual potential as effective cancer therapies." (PMID 39492832, 2024). "In turn, tumor cells secrete NGF, promoting tumor innervation, with inhibition of the Trk-NGF axis reducing the growth of PDAC tumors in mice." (PMID 38398185, 2024). "The high expression of NGF is closely related to the proliferation, invasion and migration of tumor cells." (PMID 38694509, 2024). "In in vivo xenograft models, the overexpression of NGF was shown to enhance tumor growth, while the oral administration of the TrK inhibitor larotrectinib markedly antagonized NGF-promoted M2 macrophage expression and tumor progression." (PMID 39247831, 2024). "They discovered that the tumor cells synthesized and released a distinctive protein, later named “nerve growth factor” (NGF), which was responsible for eliciting the maintenance and differentiation of both sympathetic and sensory neurons." (PMID 39596862, 2024). "It is known that the extracellular release of neurotrophic factors, such as nerve growth factor, by tumor cells can promote cancer development." (PMID 38667297, 2024). "NGF is an important neurotrophic factor shown to promote tumor cell survival, cell motility, and invasion." (PMID 38816365, 2024). "Larotrectinib exhibited excellent tumor-targeting effects by inhibiting the NGF-induced growth of tumors and lung metastasis." (PMID 38816365, 2024). "A tumor-suppressive effect of NGF was also observed in prostate tumors by facilitating maturation of tumor blood vessels by migrating smooth muscle cells, and regulating tumor tissue blood flow." (PMID 38375479, 2024). "Consistently, PREX1 was downregulated in the NGF/NGFR low‐expression tumor tissues of HCC patients and also in the NGF and NGFR low‐expression co‐culture system." (PMID 38204220, 2024). "Studies on anti-NGF treatments in mouse models showed that NGF impacts tumor progression and metastasis in a temporally dependent manner." (PMID 38392180, 2024). "Similar to Schwann cells, sensory nerves can also express chemokines that promote tumor cell invasion and metastasis, and under the influence of NGF, they extend towards tumors." (PMID 38567163, 2024). "This in turn activates the PKA and ERK signaling pathways, promoting tumor cell proliferation, transformation, and the secretion of neurotrophic factors such as NGF or BDNF." (PMID 38567163, 2024). "NGF released by tumor cells can act on sensory nerves, especially on Transient Receptor Potential Vanilloid 1 (TRPV1)." (PMID 39723256, 2024). "Compared with the saline control group, the GNC-siRNA group significantly reduced the expression of NGF mRNA in the tumor in situ." (PMID 39128942, 2024). "NGF released by tumor cells promotes neuritic growth, reduces apoptosis and increases proliferation of cancer cells leading to PDAC aggressiveness." (PMID 39723256, 2024).